TMEM100 (transmembrane protein 100)
Diseases named in the same sentence as TMEM100 in open-access papers (continued):
Sharing a sentence is not in itself a finding about the gene and the disease.
tumor (18 papers, 2015 to 2026). "Futher statistical analysis results showed the lower TMEM100 protein levels were associated with age, tumor diameter, tumor invasion, lymph node metastasis and metastasis." (PMID 35928881, 2022). "The tumor suppressor protein encoding TMEM100 gene was found to be targeted by five IA-related miRNA biomarkers; hsa-miR-15a-5p, hsa-miR-17-5p, hsa-miR-20a-5p and hsa-miR-106a/b-5p." (PMID 35504997, 2022). "Low TMEM100 levels are associated with poor prognosis and distant metastases in both tumor entities." (PMID 34476575, 2021). "TMEM100 or transmembrane protein 100 contains two hypothetical transmembrane domains and is associated with tumor progression." (PMID 34824999, 2021). "TMEM100 inhibited tumor cell proliferation and promoted cell apoptosis and autophagy in NSCLC cells." (PMID 41596760, 2026). "transmembrane protein 100 (TMEM100), a potential tumor suppressor, enhances autophagy and synergistically induces apoptosis in NSCLC cells." (PMID 38628670, 2024). "Meanwhile, TMEM100 acts as a tumor suppressor in various tumor cells to inhibit metastasis and proliferation." (PMID 37469758, 2023). "Six diagnostic genes were mutated in descending frequency in the tumor group: COL4A1, ABCA8, MAMDC2, FAP, TMEM100, and LY6E." (PMID 36685898, 2022). "TMEM100 is also known as a tumor-suppressing gene that is downregulated and differentially expressed in cancers." (PMID 35371319, 2022). "For instance, it has been reported that TMEM100 functions as a tumor suppressor in HCC metastasis and proliferation." (PMID 35371319, 2022). "Elevated TMEM100 level inhibits pulmonary metastasis of GC cells and enhances xenograft tumor sensitivity to 5-FU therapy." (PMID 35928881, 2022). "It has been reported that transmembrane protein 100 (TMEM100) acts as a tumor regulator in several types of cancers." (PMID 35358005, 2022). "miR-421 expression was significantly upregulated, while circ_0000567 and TMEM100 were downregulated in tumor tissues of LUAD, compared to their counterparts in normal tissues." (PMID 35371319, 2022). "As a tumor suppressor gene, TMEM100 restrained CRC malignant progression by regulating the TGF-β signaling pathway." (PMID 34422038, 2021). "Here, we assessed the TMEM100 expression in tumor and adjacent normal tissues via qRT-PCR, discovering that TMEM100 expression was noticeably low in CRC tissue in comparison with the expression in adjacent normal tissue." (PMID 34422038, 2021). "This study investigated the functional mechanism of transmembrane protein 100 (TMEM100) as a tumor inhibitor gene in CRC cells and offered a reference for the treatment of CRC." (PMID 34422038, 2021). "The current findings suggest that TMEM100 functions as a tumor suppressor in HCC metastasis and proliferation." (PMID 25978032, 2015). "TMEM100 was frequently downregulated in HCC tumor tissues compared to ANLTs." (PMID 25978032, 2015). "Since HCC is the tumor with rich vascular, we speculate that TMEM100 also play an important role in HCC." (PMID 25978032, 2015). "Interestingly, TMEM100 also plays a role as a tumor-suppressor gene." (PMID 36979916, 2023). "Recent studies have demonstrated that greater levels of TMEM100 are detected in the transition zone of the prostate when compared to the peripheral zone where the majority of aggressive tumors are detected and it is a possible candidate as a potent tumor suppressor." (PMID 25978032, 2015). "Furthermore, the effects of TMEM100 expression on tumor cells in vivo were also examined." (PMID 25978032, 2015). "COL4A1, COL6A3, FAP, and LY6E were up-regulated in the tumor group in the training set, whereas ABCA8, MAMDC2, TMEM100, and TMEM266 were down-regulated." (PMID 36685898, 2022). "Therefore, TMEM100 could function as a tumor suppressor in HCC." (PMID 25978032, 2015). "From these data, we speculate that TMEM100 might inhibit the metastasis and proliferation of HCC cells and act as a tumor suppressor in HCC." (PMID 25978032, 2015).
tumor (continued). "The overexpression of TMEM100 inhibited the migration and invasion without affecting tumor growth." (PMID 36979916, 2023). "Therefore, we speculate that TMEM100 might inhibit the metastasis and proliferation of HCC cells and act as a tumor suppressor in HCC." (PMID 25978032, 2015).
cancer (12 papers, 2019 to 2026). A tumor composed of atypical neoplastic, often pleomorphic cells that invade other tissues. "It has been reported that TMEM100 is associated with cancer tumorigenesis and progression." (PMID 35358005, 2022). "The TECs3 subtype, characterized by FBLN5 and TMEM100 expression, was linked to the EMT, a process that has been implicated in increased motility and invasiveness of many cancer types and contributes to metastasis." (PMID 40123905, 2025). "TMEM100 has also been involved in the metastasis and proliferation of cancer cell lines, and mediates inflammatory pathways and the secretion of inflammatory cytokines." (PMID 36979916, 2023). "Previous studies revealed that TMEM100 was involved in apoptosis, angiogenesis and cancer development." (PMID 35358005, 2022). "Recently, another study demonstrated that TMEM100 functions as a cancer suppressor mainly by inhibiting the TNF signaling pathway in NSCLC 35, which is consistent with our results." (PMID 35371319, 2022). "This suggests that TMEM100 is most likely to be involved in processes such as malignant tumor metastasis and the induction of microangiogenesis." (PMID 35928881, 2022). "At present, no studies have demonstrated the relationship between ADAMTS9-AS1 and ZEB1, or ADAMTS9-AS2 and ZEB1 or TMEM100 in cancer." (PMID 31827401, 2019). "With respect to the genes having interaction(s) with miRNAs, we realized four down-regulated vDEGs (TMEM100, MYH11, CHRDL1, and FAM107A) to the accompaniment of five up-regulated vDEGs (KLK10, CLDN1, SLC6A6, MMP11, and SLC7A5) being documented by the GEPIA in both COAD and READ cancer types." (PMID 35333898, 2022).
inflammation (1 paper, 2023). Aberrant reaction of the microcirculation characterized by movement of fluid and leukocytes from the blood into extravascular tissues. "Consistently, we found TMEM100 expression in TG neurons is increased after TMJ inflammation or masseter muscle injury." (PMID 37033371, 2023). "Moreover, the enhanced activity of TRPA1 in TG neurons evoked by TMJ inflammation or masseter muscle injury was suppressed by inhibition of TMEM100." (PMID 37033371, 2023).
TMEM100 also shares sentences with these, for which no sentence is quoted: non-small cell lung carcinoma (4 papers); glioblastoma (2); alveolar capillary dysplasia (1); atypical hemolytic-uremic syndrome (1); bladder cancer (1); chronic thromboembolic pulmonary hypertension (1); esophageal cancer (1); infection (1); microangiopathic hemolytic anemia (1); pulmonary mucoepidermoid carcinoma (1); renal failure (1); Thrombocytopenia (1); trigeminal neuralgia (1).